MTOR (mechanistic target of rapamycin kinase)
Diseases named in the same sentence as MTOR in open-access papers (continued):
Sharing a sentence is not in itself a finding about the gene and the disease.
tumor (continued). "Taken together, our results suggest that miR-497 and/or miR-99a can work as tumor suppressor in combination synergistically inhibit tumor growth via co-targeting IGF1R and mTOR." (PMID 28624790, 2017). "Tumour responses in TSC patients to rapamycin, an allosteric inhibitor of mTOR, or its analogs are partial and reversible probably due to feedback activation of Akt." (PMID 28938574, 2017). "Our patient's tumor demonstrated overexpression of EIF4E, an oncogene and downstream molecule of mTOR." (PMID 28993730, 2017). "TGF-beta activates the PI3K/Akt/mTOR pathway and leads to increased migratory capacity and invasiveness during Epithelial-mesenchymal transition (EMT) which facilitates tumor progression and metastasis in PDAC." (PMID 28053288, 2017). "As no real data on the role of hypoxia in pHGGs are published up to date, our first step in this work was to analyze tumor samples of pHGG and DIPG to screen if biomarkers involved in mTOR/ HIF-1α pathway were upregulated." (PMID 29069732, 2017). "Taken together, these results indicate that bosutinib effectively inhibits NB tumor growth in vivo by blocking the activities of Src and c-Abl and by blocking the PI3K/AKT/mTOR, MAPK/ERK, and JAK/STAT3 signaling pathways." (PMID 27903968, 2017). "Our above results showed that inhibition of mTOR leads to decreased CHK1 both in cultured cells and in tumor xenografts." (PMID 28484242, 2017). "Collectively, our signal transduction data implicate mTOR, RTK, ER, and Wnt/β-catenin signaling as major factors involved in the anti-proliferative mechanism of buformin that protects mammary tissues from tumor development in vivo." (PMID 28193239, 2017). "In conclusion, our results revealed that telmisartan inhibits human EAC cell proliferation and tumor growth, inducing cell cycle arrest by regulating cell cycle-related molecules via the AMPK/mTOR pathway." (PMID 28052030, 2017). "We also determined tumor tissue protein expression of p-AKT3 and p-mTOR using an immunohistochemical assay of tissues from nude mice." (PMID 29212166, 2017). "More studies are needed to dissect the roles of miR-100-5p and PI3K/Akt/mTOR in tumor brain and chemo brain and how they relate to the changes induced by TNBC tumor growth and DCP treatment." (PMID 29179434, 2017). "On the contrary when mTOR was active, knocking-down the intrinsic mTOR inhibitor TSC2, TAMs produced more IL-10 and both tumor growth and angiogenesis increased." (PMID 28197019, 2017). "The protein levels of PI3K p110α, p-Akt T380, p-Akt S473, p-mTOR and ST8SIA4 were decreased in the xenograft tumour tissues transfected with miR-146a/b antagomirs (*p < 0.05)." (PMID 28427206, 2017). "We demonstrated that both GSK2126458 and rapamycin had anti-tumour efficacy by suppressing proliferation of tumour cells but suppression by rapamycin was much stronger than by GSK2126458, probably due to its inhibition of both mTOR and Erk/1/2 activities." (PMID 28938574, 2017). "Since PD-L1 promotes Akt/mTOR activation and glycolysis in tumor cells, it is suggested that checkpoint blockade therapy may correct the metabolic competition-mediated nutrient availability imbalance between T cells and tumor cells through a direct effect on the tumor cells." (PMID 28447025, 2017). "Western blot was carried out on total protein extracted from the tumor samples to analyze activation-states of the Hh and PI3K/AKT/mTOR pathways." (PMID 28789624, 2017). "p-AKT and p-mTOR were dose-dependently reduced by ACT, whereas JNK phosphorylation was elevated in tumor tissue segments." (PMID 29348843, 2017).
tumor (continued). "HIF-1 alpha can also be modulated by multiple upstream factors, including the PI3K/AKT/mTOR pathway (see PTEN/PI3K/AKT/mTOR) and downstream pathways, affecting gene expression, metabolism, cell survival, tumorigenesis, and tumor growth." (PMID 26909338, 2016). "In MB cell lines, inhibition of mTOR strongly induced IDO1 expression and activity, corroborating its ability to recruit Treg cells in the tumor microenvironment." (PMID 27174915, 2016). "Decreased expression of DEPTOR resulted the activation of AKT/mTOR pathway, which directly phosphorylated the downstream SGK1 and its substrate NDRG1, and thus promoted proliferation of tumor cells." (PMID 26893358, 2016). "In the animal model of primary lung tumor, PFE also diminishes tumor growth/progression/angiogenesis by the suppression of NF-κB, MAP kinase pathways and mammalian target of rapamycin (mTOR) signaling." (PMID 26955879, 2016). "Western blot analysis of tumor tissue confirmed that p-AMPK was upregulated and p-mTOR downregulated during BBR treatment in vivo." (PMID 27557493, 2016). "mTOR phosphorylation was detected in all the three SDHB-related PPGLs, while it was detected only in one VHL-related tumor." (PMID 27990160, 2016). "mTOR is a downstream target of the PI3K–AKT signaling and has been demonstrated to enhance the expression of HIF1-α in immune cells recruited at the tumor lesion." (PMID 26870036, 2016). "Collectively, these results suggest that in PTC-derived cell lines miR-451a displays tumor suppressor functions and targets multiple elements of the AKT/mTOR pathway." (PMID 26871295, 2016). "The mammalian target of rapamycin (mTOR) is an effector of the PI3K signalling pathway regulated by AKT and the tumor-suppressor PTEN." (PMID 27374081, 2016). "To dissect the molecular mechanisms linking PD-1 binding to PD-L1 on tumor cells, we treated MDA-MB-231 cells with rPD-1 and assessed ERK and mTOR survival pathways." (PMID 26859684, 2016). "Overall, phenotypic and genotypic changes at the tumor cell and microenvironment levels during sunitinib response and progression are poorly understood, as are the distinct effects of VEGFR-TKIs and mTOR inhibitors on these resistant tumors." (PMID 27509260, 2016). "Immunoblotting of tumor tissue confirmed that NVP-BEZ235 blocked PI3K (AKTSER473/308, GSK3βSER9) and mTOR signaling (RPS6SER240/244, 4EBP1THR37/46) coincident with down-regulation of intra-tumoral MYCN protein." (PMID 27438153, 2016). "We also demonstrate dual inhibition of mTOR and BRD4 led to a better anti-tumor effect in c-Myc overexpressing MCC tumors." (PMID 26536665, 2016). "Although the drug-targeted proteins ER/PR and interesting mTOR/GSK3/TS2/PDK1/ER_P118 cluster had shown the consistent patterns between cells and tumor, low protein-based correlations were observed between cells and tumors." (PMID 27556158, 2016). "Particularly, SKCXCR2-derived tumor tissues induced higher activation of the NF-κB signaling pathway, while having no change in EGFR-activated signaling such as Raf, MEK, Akt, mTOR and Erk compared to SKA-derived tumors." (PMID 27723802, 2016). "Thus, combining bevacizumab with mTOR inhibition might maximize inhibition of tumor angiogenesis." (PMID 27539383, 2016). "In contrast, IPA predicted increased mTOR activity based on differentially expressed mTOR targets between KP and KPH2 tumours." (PMID 26837714, 2016). "In this study, we show that KRT17 is invariably induced in OSCC and stimulates the Akt/mTOR pathway and SLC2A1 expression, thereby facilitating tumor growth." (PMID 27512993, 2016). "Over-expression of [GRP78 and HSP27] prevented: AR-12 –induced activation of ER stress signaling and maintained mTOR activity; AR-12 –mediated down-regulation of thioredoxin, MCL-1 and c-FLIP-s; and preserved tumor cell viability." (PMID 26887051, 2016).
tumor (continued). "In HCC, the PI3K/AKT/mTOR pathway is frequently overactivated, and a clinical study has reported that the activation of the PI3K/ AKT/mTOR pathway correlates with tumor progression and reduced patient survival." (PMID 26958938, 2016). "Tumor growth became obvious at the later period (in KD8 group) when the adaptive mechanisms were exhausted, which was accompanied by ERK and mTOR upregulation." (PMID 26892894, 2016). "Finally, our in vitro data reveal the importance of the duration of PI3K/mTOR inhibition before IR for the radiosensitization of tumor cells by Hsp90 inhibitors and pave the way for future exploration of combination of molecularly targeted therapy and radiation on in vivo mouse tumor model." (PMID 27224913, 2016). "In summary, we demonstrate that ABT-869 and chemotherapies act synergistically to inhibit the tumor growth and angiogenesis in vitro and in vivo through simultaneous blockade of EGFR-, IGF1R- and VEGR2-mediated AKT/mTOR signaling pathways." (PMID 27387652, 2016). "In fact, while treatment with mTOR inhibitors induced TSCM phenotypes and favored anti-tumor responses in some models, it also promoted the development of MDSC, regulatory T cells (Tregs), and tolerogenic dendritic cells." (PMID 27007050, 2016). "In these prior studies, we demonstrated that pemetrexed and sorafenib interacted to kill tumor cells through endoplasmic reticulum stress signaling, inactivation of the PI3K/mTor pathway, and the induction of a toxic form of autophagic flux." (PMID 27213589, 2016). "In accordance, the rapamycin/metformin combination dramatically reduced tumor growth in vitro and in a mouse xenograft model, likely via inhibition of the PI3K/AKT/mTOR pathway." (PMID 27577068, 2016). "Inhibition of mTOR signaling disrupted PGRN-stimulated protein synthesis, transformation and proliferation of cervical cells in vitro and tumor formation and growth in mice in vivo." (PMID 27517315, 2016). "Tumor cells proximal to blood vessels instead express the lactate transporter MCT1, and p-S6, the latter reflecting mTOR signaling." (PMID 27134166, 2016). "Inhibition of mTOR signaling with rapamycin decreased PGRN-mediated protein synthesis, transformation and proliferation of cervical cells in vitro and PGRN-stimulated tumor formation and growth in nude mouse xenografts." (PMID 27517315, 2016). "PTEN is a tumor suppressor gene that negatively regulates PI3K signaling and downstream PI3K family members, including AKT and mammalian target of Rapamycin (mTOR)." (PMID 27285754, 2016). "RAD001 alone or in combination with docetaxel has suppressed intratumoral mTOR and SK1 signaling, however as evidenced by tumor size, it required docetaxel for clinical efficacy." (PMID 27821815, 2016). "In summary, our results show that T cells conditioned with MDSC show an increased anti-tumor activity after ACT, which correlated with a low progression of cells into effector populations and an arrest in mTOR signaling." (PMID 27007050, 2016). "We specifically analysed the influence of the mTOR-inhibitor Everolimus and MPA in a human in-vitro CAF-CCA tumour cell co-culture model." (PMID 27206490, 2016). "ATR-1suppresses xenograft tumor growth, triggers G2/M cell cycle arrest, induces apoptosis through intrinsic pathway and blocks PI3K/Akt/mTOR signaling pathway." (PMID 26931119, 2016). "The endometrioid type (Type I tumours), which exhibits an altered PI3K/PTEN/AKT/mTOR signal pathway, is oestrogen-dependent and well-differentiated with a relatively favourable prognosis." (PMID 26198045, 2016).
tumor (continued). "We show that the mTOR inhibitors suppressed invasion and migration in GBM cells in the presence of TNFα and tumor promoter PMA mediated by reduction of PKC-α activity and downregulation of NFκB." (PMID 26940200, 2016). "Using the mEERL system, we recently reported the ability of the mTOR inhibitor, rapamycin (sirolimus), to enhance CRT-induced cytotoxicity and attenuate tumor metabolism, contributing to improved immune-mediated clearance of HPV+ OPSCC." (PMID 27015118, 2016). "To further investigate the mechanism of tumor cell survival advantage upon PD-L1 ligation, we show that exposure to rPD-1 promoted ERK and mTOR growth and survival pathways leading to increased cell proliferation." (PMID 26859684, 2016). "PI3K/AKT/mTOR and JAK/STAT are the most important signaling pathways downstream of ALK and play an important role in cell growth in many tumor types." (PMID 26786851, 2016). "However, studies have suggested that the tumor-suppressive effects of ADAMTSs are linked to the deactivation of proliferation or invasion pathways, including inhibition of the ERK pathway by ADAMTS8, ADAMTS12, and ADAMTS15; and of the AKT/mTOR pathway by ADAMTS9." (PMID 27542224, 2016). "These inhibitors, which include mammalian target of rapamycin (mTOR) inhibitors and PI3K inhibitors, act directly on downstream signaling pathways to inhibit tumor cell proliferation and promote apoptosis." (PMID 27983617, 2016). "In fact, we found that 1 T SMF can suppress the mTOR inhibitor-induced EGFR reactivation and enhance the anti-tumor efficacy of mTOR inhibitors and EGFR inhibitor afatinib." (PMID 27223425, 2016). "Since our findings demonstrated that mTOR inhibitors targeted both NFκB and PKC-α, we confirmed the role of NFκB and PKC-α downstream signaling during tumor invasion." (PMID 26940200, 2016). "Inhibition of mTOR signaling with rapamycin decreased PGRN-stimulated protein synthesis, transformation and proliferation of cervical cells in vitro, and tumor formation and growth in vivo." (PMID 27517315, 2016). "A recent study showed that PKM2 expression is induced by an mTOR/HIF-1α/c-Myc glycolysis signaling network, promoting aerobic glycolysis in tumor cells." (PMID 27492148, 2016). "Further analysis is needed to investigate the tumor repressing role of GNG7 in a broader application and the mechanism by which GNG7 interacts and regulates MTOR signaling pathway." (PMID 27056891, 2016). "Pearce's group showed that glucose consumption by the tumoral cells restricts T lymphocytes, reducing mTOR activity, glycolytic capacity and IFN-γ production, thus favouring tumour progression." (PMID 27083002, 2016). "We further demonstrate that suppression of endothelial CCL5/CCR5 signaling leads to defects in mTOR/AKT pathway activation, as well as vascular and tumor growth defects in vitro and in vivo." (PMID 27863423, 2016). "Additional tumour suppressor roles have been described for miR-199a-3p which inhibits cell growth and migration and is thought to target MET, mTOR and STAT3." (PMID 26204834, 2015). "Treatment with PI3K inhibitor LY294002 reduced sphere formation while the dual PI3K/mTOR inhibitor NVP-BEZ235 reduced the CD133/AC141+CD44+ cell population in vivo and subsequently delayed tumor formation." (PMID 25595909, 2015). "In the phase I study of everolimus, 11 HCC patients had pre-treatment tumour tissues available for assessment, one patient achieved PR and the tumour showed moderate to high levels of p-AKT, p-MTOR and pS6." (PMID 25962426, 2015). "MTOR-inhibitors were found to downregulate the expression of the EWS/WT1 transcript and increase the Bax/BcL-xL ratio resulting in increased tumor cell death." (PMID 25945075, 2015). "IHC staining reaction of the tumor was present in 44-60 % for MMP2, MMP7, and MMP9, as well as in 96 % and 80 % for mTOR and p-mTOR, respectively." (PMID 26652716, 2015).
tumor (continued). "IDO expression can be blocked by inhibitors of c-KIT or mTOR (downstream of the c-KIT/PI3K/AKT pathway), with resultant enhancement of anti-tumor T cell responses, but the potential role of PI3K/AKT/CREB signaling or STAT3 activation has not been addressed." (PMID 26343197, 2015). "Signaling analyses revealed that AMPK/mTOR and β3 integrin were required for the induction of CD133 and tumor formation by CD90." (PMID 26556861, 2015). "Inhibition of the insulin/IGF-1/PI3K/mTOR signaling pathway either genetically or by treatment with the FDA-approved pharmaceutical rapamycin promotes longevity and inhibits tumor growth in model organisms." (PMID 26378060, 2015). "PTEN's tumor-suppressing function largely relies on the protein's phosphatase activity and subsequent antagonism of the PI3K/AKT/mammalian target of rapamycin (mTOR) pathway." (PMID 26655726, 2015). "Western blot confirmed that Ad-TERTp-E1A-1504 and Ad-ΔE1-1504 significantly suppressed EphA3 and AKT, mTOR and 4-ebp1 phosphorylation compared with Ad-TERTp-E1A-NC and Ad-ΔE1-NC, respectively, in TERT- and EphA3-positive tumor cells." (PMID 25978371, 2015). "Together, genes involved in the pathway, consisting of MTOR, PTEN, PIK3CA, AKT2, and others, have alterations in 26–28% of ccRCC tumours." (PMID 26448938, 2015). "Dasatinib interfered with the interaction between Lyn and CD19 or PI3K p85, resulting in reduced phosphorylation of Akt/mTOR in BTZ-resistant cells and significant inhibition of tumor size in a BTZ-resistant xenograft in mouse." (PMID 26517678, 2015). "Immunohistochemistry analysis of the tumor samples from the HED mice also demonstrated increased activation of AKT and mTOR." (PMID 26053184, 2015). "Comparing the primary tumor with the BCXs, we did observe increased activity of the PI3K/Akt/mTOR pathway." (PMID 26325287, 2015). "Inhibition of mTOR signaling by rapamycin and WYE-354 in tumor tissues obtained at the end of the in vivo studies was assessed by Western blot analysis." (PMID 26397134, 2015). "Rapalog mTOR inhibition decreases Vascular Endothelial Growth Factor (VEGF) production by the tumor to reduce tumor neovascularization and inhibit tumor growth." (PMID 26295809, 2015). "Both drugs alone or in combination significantly inhibited primary tumor growth, indicating a role for targeting MAPK and/or PI3K/mTOR signaling in vivo." (PMID 26506415, 2015). "Here, we examined the efficacy of combining NVP-LDE-225 (PI3K/mTOR inhibitor) and NVP-BEZ-235 (Smoothened inhibitor) on pancreatic CSCs characteristics, microRNA regulatory network, and tumor growth." (PMID 26451606, 2015). "By contrast, more fully targeting mTOR with RAD001 and a PI3K/mTOR dual inhibitor showed greater efficacy by increasing autophagy/mitophagy in tumors and decreasing tumor size in a mouse model of HCC." (PMID 26561802, 2015). "The regulation of mTOR by SEMA3F was found in several cell types, including T cells, endothelial cells and tumor cell lines, all of which are well established to utilize this signaling pathway for cellular activation, differentiation and proliferation." (PMID 26156437, 2015). "Therefore, PI3K and mTOR pathway inhibitors may be relevant in a tumor with PDGFRA amplification." (PMID 26510912, 2015). "It has been reported that AMPK activation is required in metformin-induced anti-tumor phenomena, while other studies showed that metformin exerts its action through AMPK-independent pathways such as the mTOR, TGF-β pathway." (PMID 26196392, 2015). "Regarding mTOR and FASN inhibition in vivo, EGCG (30 mg/kg for 3d/w) reduced tumor growth in the HER2-PDX model after 21 days of treatment." (PMID 26107737, 2015). "Next, an immunohistochemical staining was performed of four molecules in the PI3K/Akt/mTOR signaling axis including PI3K, Akt, mTOR, and p-70s6k1 within the primary tumor." (PMID 25788964, 2015).